LMNB1 (lamin B1)
Diseases named in the same sentence as LMNB1 in open-access papers (continued):
Sharing a sentence is not in itself a finding about the gene and the disease.
tumor (continued). "We observe a reduction of lamin B1 in HGPS, EDMD2 cells and in A549 and MCF7 tumor cells, as compared to non-transformed wild type fibroblasts." (PMID 36096808, 2022). "Based on the findings from TIMER, we proposed that LMNB1, TK1, ZWINT, and RACGAP1 are mainly expressed in PCa cells rather than immune cells, and their functions do not relate to immunological regulation of the tumor microenvironment." (PMID 31306099, 2019).
infection (17 papers, 2011 to 2024). The state of being infected such as from the introduction of a foreign agent such as serum, vaccine, antigenic substance or organism. "We found that a sustained reduction or complete loss of lamin B1 significantly increased HP-PsV infection rate." (PMID 38485766, 2024). "Thus, we conclude that depletion of lamin B1 causes a general increase in HP-PsV infection rate." (PMID 38485766, 2024). "At 24 hpi, the level of lamin B1 was reduced to 70% of that in control cells, and at later times post‐infection, the level of lamin B1 increased gradually up to 152% at 40 hpi compared with that in mock‐infected cells." (PMID 39288210, 2024). "The proportion of LMNB1 mislocalization reached more than 60% in MSNs at 21- and 30-days post infection (dpi), compared with around 20 ~ 40% in other neural subtypes." (PMID 38360694, 2024). "To determine the expression of cellular senescence-related mRNA, we analyzed CDKN2A, CDKN1A, MMP3, and Lamin B1 in the slices 8 d post infection." (PMID 37163429, 2023). "First, we analyzed by immunofluorescence microscopy the expression of lamin B1 and lamin A/C in primary B cells from healthy donors before and 24 hours after infection with EBV (B95.8 virus strain)." (PMID 35421198, 2022). "It has been found that SARS-CoV-2 leads to increased expression levels of senescence markers such as p16, p21 and Lamin B1(LMNB1) as well as SASP factors in cultured human bronchial epithelial cells 14 days after infection when the virus was undetectable." (PMID 36059478, 2022). "NMuMG cells transfected with human mCerulean-lamin B1 were subjected to short hairpin RNA (shRNA) lentivirus infection (with a control or human lamin B1-specific shRNA)." (PMID 30143639, 2018). "The cells expressing WT or K134R LMNB1 displayed the known disruption of the nuclear periphery late in infection, with infoldings of the lamina and the formation of a kidney-shape nucleus." (PMID 30470744, 2018). "Altogether, these results suggest that LMNB1 acetylation can impact lamin regulation during infection." (PMID 30470744, 2018). "We found that reduction or complete loss of LMNB1 enhances HP-PsV infection, but without significantly increasing the number of HP-PsV transcripts." (PMID 38485766, 2024). "However, we have shown that HaCaT cells respond as hypersensitive to HP-PsV infection and show a similar autophagic defect as HeLa cells upon LMNB1 kd, indicating that lamin B1 curtails early HPV infection in a cell-independent manner." (PMID 38485766, 2024). "The site-specific increase in LMNB1 acetylation late in infection and our functional studies led us to propose a model in which K134 acetylation acts in host defense by inhibiting the disruption of the nuclear lamina late in infection and thereby suppressing viral capsid egress from the nucleus." (PMID 30470744, 2018). "The increase in acetylation late in infection, in conjunction with this striking impact on virus titers, led us to propose that LMNB1 K134 acetylation may affect nuclear egress of viral capsids." (PMID 30470744, 2018). "Lamin B1 is down-regulated in mouse brain tissues 7 days after infection with T. gondii cysts." (PMID 23587304, 2013). "However, altered lamin expression is common in gastrointestinal neoplasms and reduced expression of either lamin A/C or lamin B1 is a marker of potential malignancy in the gastrointestinal tract in humans, thus their role in the infection with E. caproni needs to be further characterised." (PMID 26390031, 2015). "Also in these cells, a significant increase of both the infection ratio and EGFP intensity was observed after siRNA-mediated downregulation of LMNB1." (PMID 38485766, 2024). "Our K134R mutant studies suggest that an ubiquitination event at this site is not needed for the infection-induced local disruption of LMNB1." (PMID 30470744, 2018).
infection (continued). "Western blotting performed on extracts from both cell types collected at 7 days post-infection showed that AKTIP depletion results in a substantial decrease in lamin A compared with control cells, without affecting lamin C and lamin B1 levels." (PMID 27512140, 2016).
neurodegenerative disease (10 papers, 2019 to 2025). A disorder of the central nervous system characterized by gradual and progressive loss of neural tissue and neurologic function. "Gene duplications of lamin B1 can cause autosomal dominant leukodystrophy, a neurodegenerative disease characterized by demyelination." (PMID 40013266, 2025). "These demonstrate that LMNB1 hypofunction plays a pathogenic role in the development of neurodegenerative diseases." (PMID 38360694, 2024). "Interestingly, the balance is also important in aging because lamin B1 has been linked to age-related neurodegenerative diseases." (PMID 39518916, 2024). "While LMNB1 decrease is an important hallmark of aging, it must be cautious to conclude whether the pathology is sorely due to aging or the pathogenic genes, particularly in aging-related neurodegenerative diseases." (PMID 38360694, 2024). "Moreover, in the aging brain lamin B1 decline has not only been associated with loss of hippocampal neurogenic capability and astrocytic nuclear anomalies but also with neurodegenerative diseases such as AD and PD." (PMID 37720548, 2023). "Given the growing attention on nuclear biology in neurodegenerative diseases, we also examined LMNB1 expression in NPCs and showed that the nuclear morphology of HD-NPCs was largely deformed, along with a decrease in nuclear circularity." (PMID 38360694, 2024). "The effect of the PQBP3/NOL7-PSME3 axis on additional target proteins other than Lamin B1 and in other types of neurodegenerative diseases should be investigated in future studies." (PMID 39103492, 2024). "On the other hand, overexpression of lamin B1 leads to the adult-onset neurodegenerative disease known as Autosomal Dominant Leukodystrophy." (PMID 37720548, 2023). "Autosomal dominant leukodystrophy (ADLD) is an extremely rare and fatal neurodegenerative disease due to the overexpression of the nuclear lamina component Lamin B1." (PMID 34685544, 2021). "The pathology of LMNB1 has also been studied in other neurodegenerative diseases." (PMID 38360694, 2024). "Activation of LMNB1 can significantly delay cell senescence and alleviate degenerative diseases, suggesting that LMNB1-induced nucleophagy may have a protective effect." (PMID 35408965, 2022). "Conversely, nuclear clefts detected with lamin B1 antibody were also present in other neurodegenerative diseases; they likely reflect age-dependent changes but could nonetheless comprise a comorbidity to exacerbate toxic effects of tau accumulation." (PMID 34503506, 2021).
neurological disorder (7 papers, 2015 to 2026). "It has been established that aberrant LMNB1 expression is linked to the development of neurological disorders and tumors." (PMID 35712471, 2022). "It has been proven that abnormal LMNB1 expression is linked to neurological diseases and tumors." (PMID 35712471, 2022). "Thus the disease is caused by increased levels of lamin B1 protein produced by the presence of a functional extra copy of the LMNB1 gene, making ADLD as part of a growing number of neurological disorders caused by gene copy number variation." (PMID 25701871, 2015). "Concluding, given that the aberrant cellular mechanisms are evident in various neurological disorders and that Lamin B1 has a central and complicated role in cell cycle regulation, the alteration of signaling pathways might represent an important event underlying the disease phenotype." (PMID 33034697, 2021).
adenocarcinoma (2 papers, 2019 to 2022). A common cancer characterized by the presence of malignant glandular cells. "Immunostainings using two different antibodies revealed lower expression of lamin B1 in SCLC and a progressive loss of lamin B1 in high-grade adenocarcinoma and SCC, which have a significantly worse prognosis compared with lower grade tumors." (PMID 31015297, 2019).
hematological malignancies (2 papers, 2023 to 2024). "Our observations related to lamin B1 redistribution differ from previous reports and might be of particular interest for hematological malignancies and immune cells, where lamin A expression is more restricted." (PMID 37801090, 2023).
movement disorder (1 paper, 2019). Neurological conditions resulting in abnormal voluntary or involuntary movement, which may impact the speed, fluency, quality and ease of movement. "Furthermore, the non-recurrent mutation of LMNB1 and potential compensatory mechanisms with individual differences may be interpreted as part of the reason why only a few patients present movement disorders in this family." (PMID 31695592, 2019).
LMNB1 also shares sentences with these, for which no sentence is quoted: acquired partial lipodystrophy (2 papers); anencephaly (2); Ataxia (2); cardiomyopathy (2); genetic disease (2); leukodystrophy (2); peripheral neuropathies (2); renal cell carcinoma (2); type 1 diabetes (2); abortion (1); Adrenocortical carcinoma (1); alcoholic fatty liver disease (1); ameloblastoma (1); autoimmune disease (1); Azoospermia (1); bladder urothelial carcinoma (1); demyelinating disorder (1); diabetic kidney disease (1); endometrioid carcinomas (1); epilepsy (1); follicular lymphoma (1); frontotemporal dementia (1); gastric adenocarcinoma (1); gastrointestinal neoplasms (1); head and neck cancer (1); head and neck squamous cell carcinoma (1); Hodgkins lymphoma (1); human papillomavirus infection (1); insulinoma (1); ischemic heart disease (1).
A further 26 diseases each share a sentence with LMNB1 in 1 paper.